TNF (tumor necrosis factor)
Diseases named in the same sentence as TNF in open-access papers (continued):
Sharing a sentence is not in itself a finding about the gene and the disease.
psoriasis (continued). "CD11c+CD1c−CD141− dermal iDC, including TNF-α and inducible nitric oxide synthase (iNOS)-producing DC (Tip-DC) and slanDC, have been identified in the dermis of psoriasis patients, and they seem to play a pivotal role in the pathogenesis of psoriasis." (PMID 35837394, 2022). "We next analyzed the correlations across cytokines, because cytokines such as IL-17A and TNF-α were well known to work synergistically in human keratinocytes to promote inflammation in psoriasis." (PMID 36118416, 2022). "For example, serum hsa-miR-142-3p is significantly downregulated in patients with psoriasis after anti-tumor necrosis factor-α (TNF–α) therapy." (PMID 35665333, 2022). "In another study, 69 patients with psoriasis who started treatment with secukinumab primarily due to failure of anti-TNF and/or anti-IL12-23 treatment were evaluated." (PMID 35843765, 2022). "The interleukin (IL)-17/tumor necrosis factor-α (TNFα)/IL-23 axis is currently considered to be crucial in the pathogenesis of psoriasis." (PMID 36212052, 2022). "The incidence of psoriasis induced by TNF-α antagonists is higher than other autoimmune diseases, and IFX treatment for IBD is safer than ADA." (PMID 34678884, 2021). "Taken together, the ex vivo psoriasis skin model generated by tape stripping and stimulation with psoriasis cytokines (IL-17A, TNF-α and IL-22) turned out as a useful psoriasis ex vivo model, with psoriasin, BD2 and GLUT1 as psoriasis markers." (PMID 33801280, 2021). "Patients receiving conventional drugs had a significantly higher frequency of worsened psoriasis than patients receiving anti-TNF-α or anti-IL drugs." (PMID 34945136, 2021). "Imiquimod-induced psoriasis mice model and TNF-α or IL-17A induced HaCAT cells, an experimental model in vitro for psoriasis, were constructed." (PMID 34674702, 2021). "Potent pro-inflammatory cytokines such as TNF-α and IL–6 are capable of inducing proliferation activities and play a major role in the pathogenesis of psoriasis." (PMID 34947782, 2021). "In summary, treatment of HPK with the cytokines IL-17A, IL-22 and TNF-α results in a psoriasis-like phenotype." (PMID 33801280, 2021). "Currently, there are 11 FDA-approved biologics to treat psoriasis targeting the important TNF-α/IL-23/IL-17 inflammatory axis." (PMID 34884596, 2021). "Different forms or analogs of fumaric acid esters and apremilast and different monoclonal antibodies against TNF-α, IL-17, and IL-23 are also in the stage of clinical development for psoriasis treatment." (PMID 34371756, 2021). "As outlined in the section on eczema, most patients display an overlap between psoriasis and eczema which has been reported to be 10 times more frequent than true psoriasis in IBD patients receiving anti-TNF-α." (PMID 33802483, 2021). "The invention of biological agents has greatly improved the treatment outcomes of psoriasis, including inhibitors of tumor necrosis factor (TNF)-α, interleukin (IL)-17, and IL-12/23." (PMID 34276352, 2021). "Further studies are certainly needed to further investigate the role in the systemic involvement of psoriasis of other cells and molecules than IL-17, IL-23, and TNF-α, which currently seem “more central”." (PMID 34829740, 2021). "Oral administration of B. infantis 35624 in patients with psoriasis reduced plasma levels of TNF-α and CRP." (PMID 34501328, 2021). "TACE, in turn, can promote the occurrence of psoriasis by releasing mediators of psoriasis, including TNF-α and EGF receptor (EGFR)." (PMID 33975513, 2021). "Especially proinflammation cytokine TNF-α, the primary mediator related to the pathogenesis of psoriasis, which was released by multiple cells such as macrophages, dendritic cells, as well as B and T cells." (PMID 33858431, 2021). "TNF-α is a key proinflammatory cytokine that activates keratocytes, exacerbating an inflammatory process and constituting an inseparable element of psoriasis." (PMID 33672659, 2021).
psoriasis (continued). "We then investigated the effect of curcumol on viability and proliferation of NHEK cells stimulated with a combination of proinflammatory cytokines characteristic for psoriasis (IL-1α, IL-17A, IL-22, oncostatin M, and TNF-α; mix M5)." (PMID 34314383, 2021). "As anti-TNF and anti-IL-17A treatments were applied and both cytokines play a key role in the pathophysiology of psoriasis, the search was focused on these two biological pathways." (PMID 34746142, 2021). "The importance of Th1 functions is also emphasised by the fact that TNF-α inhibitors and methotrexate (both psoriasis treatments) reduce the expression of Th1 cytokines and reduce Th1 prevalence in those with psoriasis." (PMID 34639182, 2021). "The inflammatory response in psoriasis is driven by pro-inflammatory cytokines, primarily, interleukin-17, interleukin-23, tumor necrosis factor (TNF) and interferon-γ." (PMID 34038424, 2021). "In the past decade, clinical studies have shown that cytokines released by interleukin-17 (IL-17)-producing T cells (Th17) and dendritic cells (DCs) (e.g., IL-17, tumor necrosis factor-α, IL-12/23, and IL-22) are critical for the development of psoriasis." (PMID 34421919, 2021). "In the present study, we demonstrated for the first time the anti-inflammatory properties of CurEpiβCD-Gel in an in vitro model of psoriasis, established using HaCaT keratinocytes treated with TNF-α." (PMID 34948364, 2021). "3-HKA has protective effects in an experimental mouse model of psoriasis by decreasing skin thickness, erythema, scaling and fissuring, reducing TNF, IL-1β, IFN-γ, and IL-17 production, and inhibiting generation of effector CD8+ T cells." (PMID 34290243, 2021). "Infliximab, a chimeric monoclonal antibody that specifically binds TNF-α, has been reported to be beneficial in two young women with NS, demonstrating the joint inflammatory pathogenesis between psoriasis and NS." (PMID 34041207, 2021). "Although patients with moderate to severe psoriasis live about 6 years less than healthy individuals, the use of TNF-α inhibitors resulted in a longer lifespan than that of the healthy population." (PMID 34441936, 2021). "Coronary microvascular dysfunction as a result of systematic inflammation in psoriasis patients was ameliorated manifested as an increase in the coronary flow reserve (CFR) from 2.2 ± 0.7 to 3.02 ± 0.8 (p < 0.0001) after anti-TNF-α therapy." (PMID 34803716, 2021). "The most commonly involved inflammatory markers observed in the pathogenesis of both depression and Psoriasis are IL-6, IL-17, IL-13, IL-23, IL-10, IL-1β, and type A cytokines (TNF-α, IL-2, INF-γ) through Th1 and Th17 lymphocytes mediated processes." (PMID 34183985, 2021). "The psoriasis pathogenesis depends on environmental and genetic factors and involves communication between different immune cells through cytokines such as tumor necrosis factor-α (TNFα), IFN-γ, IL-17, IL-22 and IL-23." (PMID 34445713, 2021). "In this study, a combination of IL-1α, IL-17A, IL-22, oncostatin M, and TNF-α (mix M5) was used to trigger psoriasis-like changes in NHEK cells in vitro." (PMID 34314383, 2021). "Levels of cytokines such as IL-6, TNF-α, angiogenic factors, and adhesion molecules are elevated in obesity psoriasis and ischaemic heart disease." (PMID 35010995, 2021). "TNF-α plays a key role in the pathogenesis of psoriasis due to its stimulating effect on the proliferation of keratinocytes." (PMID 35010995, 2021). "Tumor-necrosis factor α, interleukin (IL) 12 and IL17 have been previously associated with psoriasis and successfully targeted by monoclonal antibodies." (PMID 33717124, 2021). "Studies reporting the prevalence of onychomycosis in psoriasis patients who were on biologic treatment mainly included patients receiving anti-TNF treatment." (PMID 34938812, 2021).
psoriasis (continued). "The administration of RA was demonstrated to statistically reduce the levels of IL-6, IL-8, IL-1β, TNF-α, NF-κB in this induced inflammatory reaction of epidermal keratinocytes, suggesting a potential efficacy of RA for psoriasis." (PMID 34371691, 2021). "Psoriasis is a chronic inflammatory skin disease characterized by accelerated tumor necrosis factor-α/interleukin (IL)-23/IL-17 axis." (PMID 34501328, 2021). "Hyperproliferation of keratinocytes and activation of T-cells in the epidermis stimulate the expression of cytokines, such as TNF-α, IL-17, and IL-23, followed by a proinflammatory state in the skin and finally psoriasis." (PMID 34281197, 2021). "Totally, many cells (like T cells and neutrophils) and cytokines such as TNF-alpha are involved in psoriasis development as a known autoimmune disease." (PMID 33936220, 2021). "TNF alpha concentration in patients with psoriasis decreases significantly after UVB irradiation (10.45 pg/mL vs. 3.31 pg/mL; p < 0.01)." (PMID 34208603, 2021). "Therapeutic interventions in IBD and psoriasis overlap, as IL-12/23 and TNFα blockage seems to be beneficial in both conditions (psoriasis and IBD)." (PMID 34945280, 2021). "Its role can be more prominent in psoriasis due to elevated levels of TNF-alpha in both patients' blood and skin lesions." (PMID 33936220, 2021). "In these cases, psoriasis-specific pro-inflammatory cytokines such as IL-1, IL-6, and TNF-alpha occur at much higher levels than usual in maternal serum or umbilical cord blood." (PMID 34441010, 2021). "Natural killer (NK) cells and monocytes activated by GPR55 can produce proinflammatory factors such as IL-12 and TNF-α, which have critical roles in the pathogeneses of psoriasis and CVDs." (PMID 33602246, 2021). "TNF-α, IFN-γ, IL-17, and IL-22 lead to keratinocyte proliferation which causes increased inflammation and formation of plaques found in psoriasis." (PMID 34884596, 2021). "Herein, the MPA-CUR conjugate was synthesized and evaluated for antipsoriatic activity using TNF-α-induced psoriasis-like proliferation of HaCaT cells." (PMID 34201974, 2021). "This system generated a synergistic effect by reducing the severity of psoriatic plaques in an imiquimod‐induced psoriasis mouse model compared to treatment with tacrolimus alone or TNF‐α siRNA‐loaded nanocarriers alone." (PMID 34589595, 2021). "TNF-α also plays a pivotal role in the proinflammatory cascade in psoriasis, where current clinical treatments have revolved around the use of monoclonal anti-TNF antibodies to help reduce local inflammation of the skin." (PMID 33883270, 2021). "About 16.6% of RD patients, 14.5% of IBD patients, and 16.0% of psoriasis patients switched at least once, mainly to another TNFα‐i." (PMID 34302442, 2021). "Patients with psoriasis have a higher predisposition to develop IBD; likewise, there’s a high risk of iatrogenic psoriasis lesions in patients with IBD undergoing anti-TNF treatment." (PMID 34548985, 2021). "The maintenance phase of psoriasis is primarily mediated by the adaptive immune system through the TNF-α/IL-23/IL-17 axis." (PMID 34884596, 2021). "Psoriasis development was associated with an increase in the level of angiopoietin-2 and HGF by 25%, of PDGF by 80%, of TNFα and VEGF twice, and of FGF three times as compared to healthy cells." (PMID 34691360, 2021). "The results indicated that SHR168442 gave excellent efficacy in both preclinical mouse psoriasis models with favorable PK profile and significant suppression of signature cytokines, IL-17, TNFα and IL-6." (PMID 33911101, 2021). "Identification of pro-inflammatory cytokines such as tumor necrosis factor (TNF)α, IL-17, and IL-23 as therapeutic targets allowed the development of several anti-cytokine monoclonal antibodies that revolutionized treatment of psoriasis." (PMID 33919434, 2021). "In patients with psoriasis, TNF-α is found in blood serum and skin lesions, while it is absent in healthy skin." (PMID 35010995, 2021).
psoriasis (continued). "One year after the index date, 62.4% of RD patients, 63.4% of IBD patients, and 58.7% of psoriasis patients were still using their index TNFα inhibitor." (PMID 34302442, 2021). "A study has demonstrated, through an interesting bioinformatics approach, that the dominant pro-inflammatory signals linking atherosclerosis and psoriasis are that of TNF-α and INF-γ." (PMID 34829740, 2021). "With the first generation biologics (TNFα inhibitors), it was shown that discontinuing biologic treatment resulted in quick exacerbations of psoriasis." (PMID 34656148, 2021). "Anti-TNF drugs can also lead to the development of psoriasis-like skin lesions called paradoxical psoriasis, in about 2–5% of the treated patients, a condition, which, unfortunately, frequently requires the complete cessation of the treatment." (PMID 34201546, 2021). "Cytokines, such as IL-17, IL-22, IL-12, IL-23, and tumor necrosis factor alpha (TNF-α) are secreted from T-helper lymphocytes (Th), especially Th1 and Th17 subtypes, which have many roles in the pathogenesis of psoriasis." (PMID 33356031, 2021). "In the animal model used in this study, the serum in IMQ-treated mouse showed an elevated level of M1-related cytokines (TNF-α, IL-6, IL-23) along with the decrease of the serum IL-10 level, which was accorded with human psoriasis." (PMID 33858431, 2021). "By controlling TNF and Reg-1 transcripts, Reg-3 can be involved in the pathophysiology of psoriasis." (PMID 34298932, 2021). "Psoriasis is a disease with a proinflammatory base, in which an increased expression of leptin, tumor necrosis factor alpha (TNF-α), interleukin (IL) IL-12/23, IL-6, is observed." (PMID 33562571, 2021). "It has long been known that TNFα, as a signaling molecule, not only induces a proinflammatory response of cells but is also a factor actively promoting the development of psoriasis." (PMID 34691360, 2021). "Based on our understanding of the immunological control of psoriatic inflammation, biologics targeting the TNF-α, IL-17, and IL-23 signaling pathways have been developed to treat patients with moderate-to-severe psoriasis." (PMID 34371756, 2021). "CD was found to decrease the serum levels of psoriasis-related inflammation mediators (i.e., TNF-α, IgG2a, and MPO)." (PMID 34641629, 2021). "Adults with inflammatory arthropathies, connective tissue diseases, psoriasis, or inflammatory bowel disease on biological therapy such as anti-TNFα, rituximab, tocilizumab, abatacept, or anakinra were included in this study." (PMID 33671007, 2021). "The pro-inflammatory cytokines, such as IL-6, TNF-α, IL-1β, IL-22, and IL-17A, have been reported to be up-regulated in psoriatic lesioned tissue and serum, and these cytokines likely drive the psoriasis pathogenesis." (PMID 33323018, 2021). "Significant downregulation of mRNA levels of several psoriasis‐related genes, including IL‐23, IL‐17, IL‐36, and TNF‐α, was achieved." (PMID 34589595, 2021). "To investigate the influence of ATG5 and paeonol intervention on psoriasis, we established an in vitro psoriatic model using IL-22/TNF-α stimuli and treated it with paeonol." (PMID 34113484, 2021). "The conclusion was drawn that the incidence of psoriasis is higher in the pediatric IBD patients administrated with TNF-antagonist." (PMID 34678884, 2021). "Some inflammatory cytokines including tumor necrosis factor-α (TNF-α), interleukin- (IL-) 23, and IL-17 derived from T cells and dendritic cells, macrophages, and keratinocytes play a key role in the pathogenesis of psoriasis." (PMID 34603060, 2021). "Many pieces of evidence demonstrated the pivotal role of TNF-alpha in psoriasis pathogenesis like elevated levels of TNF-alpha in both blood and skin lesions at the disease activation time." (PMID 33936220, 2021).
psoriasis (continued). "A study with 478 patients from Denmark diagnosed with moderate-to-severe psoriasis and treated with anti-TNF medication (n = 376) and with UTK (n = 230) assessed the effect of these polymorphisms on the treatment response (PASI 75 at 3 months)." (PMID 33921427, 2021). "For example, the scFv Brolucizumab, directed against VEGF, is approved for the treatment of macular degeneration, and DLX105, directed against tumor necrosis factor alpha, demonstrated a positive outcome on psoriasis biomarkers in a clinical study." (PMID 34939999, 2021). "Mixed cytokines, including IL-17A, IL-22, oncostatin M, IL-1α, and TNF-α (M5), were used to simulate HaCaT keratinocytes to establish a psoriatic keratinocyte model that generates some phenotypic features in common psoriasis in vitro." (PMID 34202301, 2021). "In an observational, case–control Spanish study, the cumulative incidence of psoriasis was 1.0% after 1 year from starting anti-TNF-α treatment, 2.5% after 5 years, and 4.5% after 10 years." (PMID 33477990, 2021). "A study of 22 patients who were diagnosed with cutaneous T-cell lymphoma (CTCL) after failing to respond to TNF-a inhibitors found that 3⁄4 of patients were being treated for what they believed were inflammatory skin conditions (mainly psoriasis and AD)." (PMID 34440162, 2021). "In an IBD cohort of 1004 patients previously treated with anti-TNF-α agents including infliximab, adalimumab, and certolizumab, psoriasis-like lesions were observed in 27 patients, mostly affected by CD." (PMID 33477990, 2021). "Most of these targets exhibited abnormal expression and were designated as the therapeutic targets in psoriasis, such as the cytokines and chemokines (IL-1β, IL-6, TNF, IFN-γ, CXCL8, CCL2)." (PMID 34168554, 2021). "In the multivariable analysis, the following variables were included: receiving nutritional advice (group N), age, full- or part-time employment, psoriasis, disease duration, use of TNF inhibitors, concomitant treatments, BMI, patient VAS global, and CRP." (PMID 34416917, 2021). "While in groups in which psoriasis was induced and treated with different formulations showed reduced levels of both TNF-α and IL–6." (PMID 34947782, 2021). "Another study further confirmed that anti-TNF treatment improves the metabolic profile of patients with psoriasis by downregulating their total cholesterol and low-density lipoprotein (LDL) levels." (PMID 34367173, 2021). "The positive feedback loop between immune cells and resident cells in psoriasis can further facilitate more TNF generation in lesional skin." (PMID 34638757, 2021). "Although these immunotherapeutic agents are highly effective in the treatment of skin and joints psoriasis, they neutralize the effects of TNF on different cell types while it can be vital for the beneficial immune responses." (PMID 33936220, 2021). "Administration of these nanofibers as an immunomodulatory vaccine successfully lowered inflammatory signatures in models of TNF-driven septic shock and psoriasis." (PMID 33883270, 2021). "Multiple biologics are available for the treatment of pediatric psoriasis that provide specific inhibition of immune-mediated pathways involving tumor necrosis factor (TNF), IL-17, and IL-23." (PMID 34440162, 2021). "In psoriasis, IL-17-producing T helper cells (Th17) are central in the pathogenesis and Th17-related cytokines such as IL-17A, IL-17F and IL-22, together with TNFα, drive epidermal hyperplasia." (PMID 34616394, 2021). "Previous studies have shown that TNF-α/IL-23/IL-17/1L-22 axis played a crucial role in the development of psoriasis." (PMID 34675805, 2021). "Psoriasis is a chronic inflammatory, immune-mediated disease which is induced by many pro-inflammatory cytokines, such as IL-17A, TNF-a, IL-22 and IL-23." (PMID 34992498, 2021).